ACKR3 (atypical chemokine receptor 3)
Diseases named in the same sentence as ACKR3 in open-access papers (continued):
Sharing a sentence is not in itself a finding about the gene and the disease.
adenoma (1 paper, 2015). A neoplasm arising from the epithelium. "Interestingly, ACKR3 was expressed by all the PAs, especially in GH and PRL secreting adenomas and it was observed that its expression was significantly higher in macro- than micro-adenomas." (PMID 26441831, 2015). "Therefore, the better characterization of CXCR4/ACKR3/CXCL12 axis in PAs could pave the way for novel pharmacological approaches, especially for those adenoma subtypes (i.e., TSH and ACTH-secreting tumors, as well as NFPA) still waiting for efficacious therapeutic drugs." (PMID 26441831, 2015).
aneurysm (1 paper, 2025). Bulging or ballooning in an area of an artery secondary to arterial wall weakening. "We found that this axis played a role in cell–cell interactions, which is confirmed by the increased expression of Cxcr4 in the aneurysm and increased expression of Ackr3 in the vascular wall and adventitia." (PMID 40440080, 2025). "For example, the higher expression of Cxcr4 and lower expression of Ackr3 in the aneurysm may contribute to the progression of AAA." (PMID 40440080, 2025). "Thus, the Cxcl12–Cxcr4/Ackr3 axis may play pivotal roles in the initiation, development, and progression of aneurysm." (PMID 40440080, 2025). "By immunostaining, we confirmed the increased expression of Cxcr4 mostly in the aneurysm of the AAA group and increased expression of Ackr3 mostly in the vascular wall and adventitia of the AAA group." (PMID 40440080, 2025).
brain cancer (1 paper, 2017). A primary or metastatic malignant neoplasm affecting the brain. "Ackr3 inhibition or inactivation reduces head and neck tumour growth and increases survival of mice with brain cancer." (PMID 27136898, 2017).
brain injury (1 paper, 2021). Acute and chronic (see also brain INJURIES, CHRONIC) injuries to the brain, including the cerebral hemispheres, CEREBELLUM, and brain STEM. "Ackr3 is considered a scavenger of the CXC chemokine CXCL12, which prevents leukocytes from entering the microvasculature of the brain; thus, upregulation of Ackr3 promotes blood-brain barrier impairment and inflammatory brain injury." (PMID 34595206, 2021).
carotid artery thrombosis (1 paper, 2022). Blood clot formation in any part of the carotid arteries. "As found in in vitro platelet function assays, ligation-induced carotid artery thrombosis was increased in Ackr3−/− compared to littermate controls." (PMID 35383158, 2022).
demyelinating disease (1 paper, 2024). A broad group of disorders that affect the myelin sheaths that cover the neurons. "In addition, in line with previous studies using a functional ACKR3 antagonist, treatment with ACT-1004-1239 was also able to reduce the demyelination induced by the toxic agent cuprizone in mice, emphasizing the pathological role of ACKR3 in preclinical models of demyelinating diseases." (PMID 38819698, 2024).
dyslipidaemia (1 paper, 2021). "In addition increased serum CXCL12 levels are found in patients with dyslipidaemia, and statins used for the treatment of dyslipidaemia have been shown to reduce CXCL12 levels (probably through ACKR3), implicating the CXCL12/ACKR3 axis as a potential therapeutic target." (PMID 34494495, 2021).
Giardia infections (1 paper, 2022). "Several cytokine receptors are differentially expressed during the Giardia infections, including IL11RA, IFNGR1, IFNGR2, IL10RA, and ACKR3." (PMID 35573800, 2022).
hemolytic-uremic syndrome (1 paper, 2023). Acute kidney injury associated with microangiopathic hemolytic anemia and thrombocytopenia. "A prothrombotic role for the CXCL12/CXCR4/ACKR3 axis has also been proposed for the thrombotic microangiopathy caused by bacterial infections with Shiga toxin-producing E. coli that leads to the hemolytic uremic syndrome (HUS)." (PMID 37954596, 2023).
HIV-1 infection (1 paper, 2019). The type species of lentivirus and the etiologic agent of acquired immunodeficiency syndrome (AIDS). "Ackr3, Pld1, and Ccr2 expression up-regulation had patterns very similar to Ccr5 and further indicate that AMPH and EIH can exacerbate HIV-1 infection." (PMID 30779732, 2019).
intervertebral disc degeneration (1 paper, 2025). "In the context of intervertebral disc degeneration (IDD), neutrophil infiltration into the extracellular matrix contributes to disease progression through the MIF/ACKR3 axis." (PMID 40756519, 2025).
leukocytosis (1 paper, 2022). "It is not clear why ACKR3 deficiency in ECs lead to leukocytosis in mice and this remains to be elucidated in further studies." (PMID 35674847, 2022).
meningioma (1 paper, 2020). A generally slow growing tumor attached to the dura mater. "In addition, ACKR3 may be also involved in meningioma tumor cell proliferation and survival." (PMID 32456359, 2020).
neurological autoimmune diseases (1 paper, 2018). "While an impact of ACKR3 has been recognized in several neurological autoimmune diseases, neuroinflammation may also result from infectious agents, including Ureaplasma species (spp)." (PMID 29792190, 2018).
prostate adenocarcinoma (1 paper, 2019). "In addition, the effect of S100A4, ACKR3, and CDH1 expression on overall survival (OS) was assessed using the TCGA-prostate adenocarcinoma (PRAD) dataset." (PMID 31895690, 2019).
vitiligo (1 paper, 2022). Generalized well circumscribed patches of leukoderma that are generally distributed over symmetric body locations and is due to autoimmune destruction of melanocytes. "ACKR3 (CXCR7) is another high-affinity receptor for CXCL12; however, there is a lack of investigations into ACKR3 in vitiligo up to date." (PMID 35096274, 2022).
tumor (348 papers, 2006 to 2026). "Tumoroids demonstrated upregulation of oncogene-associated genes (Ackr3, Adcy3, Fam222) and downregulation of tumor suppressor genes (Casz1, Frk, Homer2, Pdlim1)." (PMID 40772227, 2025). "Within the CNS, ACKR3 has high expression in glioma tumor cells, microglia, and tumor-associated vascular endothelium." (PMID 38003682, 2023). "Because ACKR3 is highly expressed in many cancers, including oncovirus cancers, it can be used as a tumor-associated antigen for the targeted destruction of cancer cells." (PMID 35159113, 2022). "While ACKR3 expression in tumor-associated vessels in IDH1-wildtype tumors predicted a better prognosis, it has reverse consequences in IDH mutated tumors." (PMID 32456359, 2020). "Ackr3 has also been implicated in hypoxia response, tumour development, cell growth, cell survival and adhesion." (PMID 27136898, 2017). "Furthermore, in gastric cancer, ACKR3 has been implicated in promoting tumor growth and metastasis via the STAT3/c-Myc pathway." (PMID 38920657, 2024). "Genes such as ACKR3 are associated with hypoxic responses and may contribute to the lymphatic spread of tumor cells." (PMID 39000413, 2024). "Analyses of key target genes involved in the tumor–bone vicious cycle showed similar patterns of gene expression in the vehicle-treated Cont-4T1 and Pth1rKD-4T1 tumors except for Il6, Ackr3 (encoding CXCR7), and Cyp19a1, which were reduced in the Pth1rKD-4T1 cells." (PMID 36692956, 2023). "ACKR3 is highly expressed, relative to the normal vasculature, by most tumor-associated blood vessels of human breast and lung cancers, as well as of melanoma, modulating tumor associated angiogenesis." (PMID 35565443, 2022). "The CXCL12/CXCR4/ACKR3 axis is not only implicated in GB, but also in extracranial tumors and is involved in tumor progression, angiogenesis, metastasis, and survival as well as contributing to immunosuppressive networks within the tumor microenvironment." (PMID 30813533, 2019). "Indeed, ACKR3 has been shown to be upregulated on various tumor cells as well as on tumor-associated vasculature, therefore potentially interfering with the CXCR3–CXCL11 interactions." (PMID 31216755, 2019). "ACKR3 (CXCR7) is overexpressed in several tumors and drives tumor cell adhesion, invasion, survival, and growth, as well as angiogenesis." (PMID 41149503, 2025). "Currently, monoclonal antibodies targeting the CXCL14/ACKR3 axis are in Phase I tumor clinical trials (NCT04857112), and our study provides a theoretical basis for expanding their indications to IPF." (PMID 40842541, 2025). "The study found that GDYO inhibits Mif-Ackr3 signaling in tumor cells and CAFs, reducing the number of regulatory T cells and tumor stem cells in TME, and ultimately inhibiting lymphoma growth." (PMID 40038692, 2025). "Future research should focus on elucidating the specific roles and mechanisms of ACKRs in BCa, particularly ACKR3, to better understand their contribution to tumor progression and to explore potential therapeutic strategies targeting these receptors." (PMID 39409924, 2024). "Mechanistically, miR-101 suppresses T-ALL tumor development by targeting the CXCL12/ACKR3/STAT3 signaling pathway." (PMID 38920657, 2024). "Still, the number of BM in mice with tumor cells expressing a miR‐100 mimic+ovACKR3 was similar to the control (p > 0.05), indicating that miR‐100 expression can negate the effect of ACKR3 overexpression." (PMID 37496297, 2023). "CXCL12-CXCR4/ACKR3 interactions promote tumor growth, adhesion, vascularization, invasion, and metastasis to CXCL12-rich organs like lungs, liver, bone marrow, and lymph nodes." (PMID 36725964, 2023). "In contrast, a TEC subpopulation expressing CXCL2, IL-6 and ACKR3 was markedly suppressed in tumor with only marginal increase after chemotherapy." (PMID 36253784, 2022).
tumor (continued). "Previous in vitro and in vivo studies have shown that higher levels of ACKR3 are correlated with increased cell proliferation and invasive migration, that is, tumor growth and metastasis." (PMID 35742971, 2022). "Some studies have found that blocking ACKR3 with the antagonist AMD3100 can improve the immunosuppressive tumor microenvironment." (PMID 35869528, 2022). "In fact, a frequent characteristic of tumor cells is the concomitant overexpression of CXCR4/ACKR3 and growth factor receptors (GFR), an important element in cell proliferation and survival." (PMID 36233192, 2022). "Our findings suggest that in certain BC subtypes, a relevant cooperation between CXCR4/ACKR3 and growth factor receptors takes place to integrate concurrent signals emanating from the tumor microenvironment and foster cancer progression." (PMID 36233192, 2022). "In many solid cancers altered expression levels of ACKR3 correlate with poor prognosis and tumor metastasis." (PMID 36713377, 2022). "The chemokine receptor system plays a relevant role in BC, where some chemokines and their cognate receptors, namely CXCL12 and its receptors CXCR4 and ACKR3 are found overexpressed and often dysregulated in both tumor and tumor microenvironment (TME) cells." (PMID 36233192, 2022). "Different downstream pathways, such as the mitogen-activated protein kinases (MAPK) cascades, convey CXCL12 signal via CXCR4/ACKR3 with roles in tumor biology." (PMID 36233192, 2022). "CCX771 is one of the ACKR3 modulators described to induce β-arrestin recruitment to the receptor and it was reported to inhibit tumor growth, lung metastasis, and tumor angiogenesis in in vivo tests." (PMID 36552863, 2022). "CXCL12 additionally promotes tumor vascularization by inducing endothelial cell differentiation, proliferation, and morphogenesis via its receptor CXCR7 (also called ACKR3)." (PMID 36568151, 2022). "In sum, our findings strongly suggest a relevant cooperation between CXCR4/ACKR3 and growth factor receptors in tumor progression, likely facilitated by the simultaneous increased abundance/functionality of these proteins in many tumor types." (PMID 36233192, 2022). "Since knock-down or pharmacological inhibition of ACKR3 has been shown to reduce tumor invasion and metastasis, ACKR3 is a promising therapeutic target for the control of tumor dissemination (for further details see Appendix 1)." (PMID 33427197, 2021). "Their scavenger receptor, atypical chemokine receptor 3 (ACKR3; CXCR7), also participates in tumor progression." (PMID 34722241, 2021). "Studies suggest that the overexpression of the CXCR7 (or ACKR3) receptor has been found in various cancers and has been shown to modulate the tumor microenvironment and tumor cell survival." (PMID 34500609, 2021). "CXCR3 and CXCL11 have reported roles in tumor development and maintenance and ACKR3 has been proposed to scavenge excess CXCL11." (PMID 34583741, 2021). "These antibodies were labelled with [89Zr] and were used to visualise CXCR4 or ACKR3 expression in murine xenograft tumours using PET imaging." (PMID 33506623, 2021). "By scavenging its chemokine ligands CXCL12 and CXCL11, ACKR3 exerts important functions in embryonic development, in the regulation of leukocyte and tumor cell migration across blood vessels and in B cell immunity/activation in germinal centers." (PMID 33857173, 2021). "ACKR3 is also found in endothelial cells as well as in tumor cells and microglia in GBM patient tissue specimens." (PMID 35008294, 2021). "ACKR3, an atypical chemokine, is also overexpressed in many types of cancer, and is involved in tumor proliferation and angiogenesis." (PMID 32253815, 2020). "Whereas, CXCR4 was characterized as a typical tumor-supporting receptor, many lines of evidence indicated CXCR7/ACKR3 can have pro-metastatic effects but in specific settings it can act in an opposite manner." (PMID 32582148, 2020).
tumor (continued). "Tumor cells and vascular endothelial cells of different tissues show an increased expression of Ackr3 and it has been suggested to include this receptor as a marker for cancer." (PMID 32161595, 2020). "While CXCR4 and CXCL12 were homogeneously expressed within tumor cells, ACKR3 was mainly identified in tumor endothelial cells but CXCL11 in pericytes." (PMID 32456359, 2020). "Several in vivo and in vitro studies have found that high levels of ACKR3 expression promote cell proliferation, invasive migration, tumor growth, and metastasis." (PMID 31895690, 2019). "ACKR3 is upregulated in tumor endothelial cells, where it is induced under hypoxic and acidic conditions, distinctive features of the tumor microenvironment." (PMID 30800123, 2019). "Targeting of ACKR3 with a monoclonal antibody in mice models of glioblastoma leads to increased tumor cell death via NK-cell mediated antibody-dependent cytotoxicity (ADCC)." (PMID 30319622, 2018). "CXCR4 and ACKR3 as well as CXCL12 are frequently overexpressed in human cancers where they contribute to tumor growth and metastasis formation." (PMID 29156704, 2017). "In breast cancer, ACKR3 expressed in trans can modulate CXCL12 levels leading to altered CXCR4-dependent tumor growth." (PMID 29156704, 2017). "It has been suggested that ACKR3 and CXCR4 cooperate in enhancing tumor growth, sometimes through separate effects on cancer cells and angiogenesis, and blocking ACKR3 has been shown to diminish growth of tumors in mouse models." (PMID 29088715, 2017). "A localized xenograft model was used to study the role of ACKR3 in VAL DLBCL tumor spreading and tissue infiltration." (PMID 29156704, 2017). "The inhibitory effect on TEM was attributed to both, the expression of ACKR3 on endothelial cells as well as on the migrating tumor cells." (PMID 29156704, 2017). "The present data unveil ACKR3 as potential therapeutic target for the control of tumor dissemination in DLBCL." (PMID 29156704, 2017). "ACKR3 is also prominently expressed in a wide range of tumors both within the tumor cells and by cells of the tumor vasculature." (PMID 27375622, 2016). "Furthermore, the MIF/ACKR3 axis is critical in various biological processes, including lymphocyte chemotaxis and tumor cell proliferation." (PMID 39896809, 2024). "Similarly, CXCR7 (ACKR3) is overexpressed in lung tumor tissues, and upregulation of CXCR7 markedly promotes A549 cell migration in vitro and enhances tumor growth and metastasis in vivo." (PMID 37496297, 2023). "ACKR3 is involved in tumor growth and metastasis and cardiac development." (PMID 35383158, 2022). "Several studies support the key role of ACKR3 in tumor invasion and metastasis." (PMID 33427197, 2021). "ACKR3 is also suggested to promote tumor growth by stimulating angiogenesis." (PMID 35008294, 2021). "Furthermore, ACKR3 is upregulated in various types of cancer and was found to be involved in tumor cell migration, rendering it a potential therapeutic target for cancer therapies." (PMID 33857173, 2021). "It was also shown that ACKR3 may enhance tumor cell proliferation and inhibit their apoptosis, thus promoting tumorigenesis." (PMID 32456359, 2020). "Upregulated expression of S100A4 and ACKR3 was detected in Doc-resistant tumor samples." (PMID 31895690, 2019). "ACKR3 may provide an advantage for tumor cells that favors their metastasis, driving cells through CXCL12 gradients by binding and degrading CXCL12–regulating bioavailability and gradient control, as it does during development." (PMID 30800123, 2019). "Moreover, western blotting and immunohistochemistry revealed altered expression of S100A4, ACKR3 and CDH1in clinical tumor samples." (PMID 31895690, 2019). "ACKR3 upregulation may occur in activated endothelial cells and may contribute to tumor angiogenesis." (PMID 31156639, 2019). "Nevertheless, the molecular mechanism of ACKR3 in tumor formation is less clear and may vary between cancers types." (PMID 29156704, 2017).